PRR20D (proline rich 20D)
Tractability: No criterion of Open Targets' tractability assessment is met for any kind of drug.
Gene: Protein-coding gene on chromosome 13 (57,160,632 to 57,163,653, forward strand). Ensembl gene ENSG00000227151.
Gene Ontology:
Molecular function: identical protein binding; protein binding
Homologues: Orthologues: dog PRR20G (38% identical). Paralogues in human: PRR20A (100% identical), PRR20B (100% identical), PRR20C (100% identical), PRR20E (100% identical), PRR20G (53% identical).